ENSG00000287640 (novel transcript)
Gene: Long non-coding RNA gene on chromosome 2 (60,383,141 to 60,385,794, forward strand). Ensembl gene ENSG00000287640.
Gene Ontology:
Molecular function: pre-mRNA 5'-splice site binding
Biological process: mRNA 5'-splice site recognition
Cellular component: U1 snRNP